MFAP4 (microfibril associated protein 4)
Description:
Could be involved in calcium-dependent cell adhesion or intercellular interactions. May contribute to the elastic fiber assembly and/or maintenance.
Tractability: Antibody: UniProt places it where antibodies can reach, with high confidence; its Gene Ontology location is reachable by antibodies, with high confidence; UniProt predicts a signal peptide or a membrane-spanning region.
Gene: Protein-coding gene on chromosome 17 (19,383,442 to 19,387,197, reverse strand). Ensembl gene ENSG00000166482.
Subcellular location: Secreted, extracellular space, extracellular matrix
Subcellular location (Human Protein Atlas): Endoplasmic reticulum; Predicted to be secreted
Pathways (Reactome):
Extracellular matrix organization: Molecules associated with elastic fibres
Gene Ontology:
Molecular function: protein binding; extracellular matrix structural constituent
Biological process: cellular response to UV-B; elastic fiber assembly; regulation of collagen metabolic process; supramolecular fiber organization; UV protection
Cellular component: extracellular matrix; extracellular region; microfibril; non-collagenous component of interstitial matrix; elastic fiber
Genetic constraint (gnomAD): Loss-of-function variants: 20 observed, 32.15 expected, observed/expected ratio (o/e) 0.62, 90% interval 0.44 to 0.9. The upper end of that interval is the gene's LOEUF score, 0.9, which puts it in group 3 of 6, group 1 being the genes least tolerant of losing a copy. Missense variants: 267 observed, 332.51 expected, observed/expected ratio (o/e) 0.8, 90% interval 0.73 to 0.89. Synonymous variants: 146 observed, 135.76 expected, observed/expected ratio (o/e) 1.08, 90% interval 0.94 to 1.23.
Homologues: Orthologues: chimpanzee MFAP4 (100% identical), macaque MFAP4 (99% identical), rabbit MFAP4 (96% identical), rat Mfap4 (95% identical), dog MFAP4 (94% identical), mouse Mfap4 (94% identical), pig MFAP4 (92% identical), guinea pig MFAP4 (81% identical), tropical clawed frog mfap4.2 (61% identical), zebrafish mfap4.1 (47% identical), zebrafish mfap4.2 (46% identical), zebrafish mfap4.13 (46% identical), and 12 more. Paralogues in human: FIBCD1 (47% identical), FCN2 (42% identical), FCN1 (41% identical), FGL2 (40% identical), TNC (39% identical), TNR (39% identical), ANGPT4 (38% identical), FGL1 (38% identical), ANGPT1 (37% identical), FCN3 (37% identical), TNN (36% identical), TNXB (36% identical), and 13 more.
Diseases named in the same sentence as MFAP4 in open-access papers:
MFAP4 is named in the same sentence as 99 diseases in open-access papers, as found by Europe PMC text mining. Sharing a sentence is not in itself a finding about the gene and the disease. The quoted sentences say what the papers report.
liver fibrosis (18 papers, 2015 to 2025). "To identify differentially expressed genes associated with BA and liver fibrosis, we employed bioinformatics approaches to analyze GEO datasets pertinent to BA, culminating in the selection of a pivotal gene, MFAP4." (PMID 40492258, 2025). "In summary, we identified MFAP4 as an important gene associated with liver fibrosis and the prognosis of BA." (PMID 40492258, 2025). "Proteomic analysis of liver tissue samples has identified upregulated MFAP4 in HBV/HCV-associated hepatic fibrosis, and several reports have suggested that serum MFAP4 levels can be used as a non-invasive tool for screening liver fibrosis." (PMID 40243889, 2025). "On this basis, MFAP4 has been proposed as a candidate diagnostic biomarker for disease staging in hepatic fibrosis and cirrhosis." (PMID 35805199, 2022). "Both tissue expression and circulating MFAP4 levels are associated with various disorders, including liver fibrosis and cancer." (PMID 35805199, 2022). "In this study, a target gene of miR-1/194/206-3p was MFAP4, which was recently identified as a biomarker for hepatic fibrosis and has been used to detect high-risk patients with severe fibrosis stages among hepatitis C patients." (PMID 28821885, 2017). "Additionally, initially identified as a biomarker of liver fibrosis, MFAP4 was subsequently confirmed its diagnostic capability in hepatitis C virus or alcohol-induced liver fibrosis." (PMID 36650606, 2023). "Moreover, extensive research has shown that serum MFAP4 levels can be used as a diagnostic predictor of varying degrees of liver cirrhosis and liver fibrosis." (PMID 34798886, 2021). "Recent studies have linked Mfap4 to liver fibrosis, cardiac dysfunction, and kidney fibrosis." (PMID 34502419, 2021). "Additionally, a research study performed a genetic screen in living organisms and discovered that reducing the expression of microfibril-associated protein 4 (Mfap4) in liver cells promotes cell growth, accelerates liver regeneration, and decreases liver fibrosis." (PMID 40913218, 2025). "Currently, MFAP4 accurately predicts the degree of liver fibrosis secondary to hepatitis and alcoholic liver disease." (PMID 40492258, 2025). "Our study reports significant differences in serum MFAP4 levels among pediatric patients with biliary atresia (BA) stratified by liver fibrosis stages, underscoring the ease of MFAP4 detection in serum and its potential to streamline fibrosis assessment." (PMID 40492258, 2025). "A limitation of this study is that no in vivo experiments were conducted to further validate the regulatory role of MFAP4 in liver fibrosis in BA." (PMID 40492258, 2025). "The relationship between serum MFAP4 levels and liver fibrosis, as well as prognosis, was investigated using ROC curve analysis." (PMID 40492258, 2025). "MFAP4 was suggested as a potential biomarker for the non-invasive assessment of hepatic fibrosis in hepatitis C patients." (PMID 37935709, 2023). "Taken together, our results show that the knockdown of Mfap4 attenuates NASH progression by reducing liver fibrosis and steatosis." (PMID 37935709, 2023). "Knockdown of Mfap4 in hepatocytes enhances cell proliferation, accelerates liver regeneration, and attenuates chronic liver disease by reducing liver fibrosis." (PMID 37935709, 2023). "Other observations have shown that both local MFAP4 expression and serum levels of MFAP4 are increased in liver fibrosis/cirrhosis and moreover are moderately regulated in COPD." (PMID 29884190, 2018). "We were able to demonstrate the applicability of MFAP4 as a serum biomarker for hepatic fibrosis in a large cohort of hepatitis C patients." (PMID 27378383, 2016). "Previously, we identified MFAP4 as a serum biomarker candidate for hepatic fibrosis and cirrhosis in hepatitis C patients." (PMID 27378383, 2016).
liver fibrosis (continued). "We detected an elevated abundance of extracellular human MFAP4 in the cirrhotic septae and recently confirmed the elevated expression of MFAP4 in hepatic fibrosis investigating tissue samples from a larger patient cohort." (PMID 27378383, 2016). "In the present study, we examined the potential of MFAP4 to serve as a new serum biomarker for the assessment of hepatic fibrosis." (PMID 27378383, 2016). "Although only little is known about its molecular function, the relevance of MFAP4 is well-established for diseases associated with remodeling of the ECM such as vascular stenosis and liver fibrosis." (PMID 27378383, 2016). "Notably, the expression of MFAP4 was higher in liver fibrosis tissues from patients compared than in those with choledochal cyst." (PMID 40492258, 2025). "Furthermore, MFAP4 expression was positively correlated with the pathological stage of liver fibrosis." (PMID 40492258, 2025). "MFAP4 serves as a surrogate for gene expression levels in serum, facilitating its convenient measurement, which potentially enables a more accessible assessment of liver fibrosis severity using serum biomarkers in clinical practice." (PMID 40492258, 2025). "Elevated serum MFAP4 levels indicate a more severe degree of liver fibrosis, which may lead to decreased autologous liver survival." (PMID 40492258, 2025). "Serum MFAP4 levels accurately reflects the degree of liver fibrosis in patients with BA." (PMID 40492258, 2025). "As liver fibrosis is associated with an alteration of the composition of the ECM, all its components (HA, PIIIPN, type 4 collagen, laminin, microfibrillar-associated protein 4—MFAP4) are under study." (PMID 39201990, 2024). "While MFAP4 expressional levels are often, but not always, regulated during disease, the circulatory MFAP4 levels are significantly correlated with liver fibrosis staging and have potential as a diagnostic biomarker for liver fibrosis and cirrhosis." (PMID 35805199, 2022). "Moreover, MFAP4, together with TE, participates in the assembly of elastin and the two proteins are upregulated in liver fibrosis and cirrhosis, and can serve as a biomarker of liver fibrosis." (PMID 34798886, 2021). "Furthermore, several studies have reported elevated serum MFAP4 levels in allergic asthma, liver disease, and liver fibrosis as well as the role of MFAP4 in inflammatory mechanisms in the lung." (PMID 31555146, 2019). "Second, MFAP4 blood levels significantly correlate with liver fibrosis suggesting that MFAP4 might interfere with tissue regeneration." (PMID 27936003, 2016). "Based on these findings, we speculated that MFAP4 plays a role in liver fibrosis." (PMID 40492258, 2025). "Furthermore, serum MFAP4 levels may serve as a predictive marker for the degree of liver fibrosis and autologous liver survival after Kasai surgery." (PMID 40492258, 2025). "Furthermore, serum MFAP4 levels may serve as predictive markers for the degree of liver fibrosis and autologous liver survival after Kasai surgery." (PMID 40492258, 2025). "Furthermore, we examined the relative mRNA expression levels of key markers related to hepatic fibrosis (Acta2, Cola2, TGF-β1, and MMP2), cirrhosis (CXCR4, SOX9, DCN, and MFAP4), and cancer (Bcl2, CDKN2a, c-Myc, and Fn1) across the experimental groups." (PMID 39851554, 2025). "In contrast, aged mice exhibited hepatic fibrosis, with increased collagen deposition and upregulation of genes related to fibrosis (Acta2, MMP2, TGF-ß1, and Col1a2), cirrhosis (CXCR4, SOX9, DCN, and MFAP4), and cancer (Bcl2, CDKN2a, c-Myc, and Fn1)." (PMID 39851554, 2025). "The aim of the present study was to elucidate the potential of MFAP4 as biomarker for hepatic fibrosis with a focus on the differentiation of no to moderate (F0–F2) and severe fibrosis stages and cirrhosis (F3 and F4, Desmet-Scheuer scoring system)." (PMID 27378383, 2016).
Cirrhosis (10 papers, 2013 to 2025). A chronic disorder of the liver in which liver tissue becomes scarred and is partially replaced by regenerative nodules and fibrotic tissue resulting in loss of liver function. "Circulatory MFAP4 has been previously associated with fibrotic deposition and cirrhosis in hepatitis C as well as other conditions leading to fibrogenesis of the liver." (PMID 34805319, 2021). "Microfibrillar-associated protein 4 (MFAP4) is a systemic biomarker that is significantly elevated in samples from patients suffering from hepatic cirrhosis." (PMID 24324779, 2013). "Recently, a search for novel biomarkers in HCV-associated hepatic cirrhosis revealed MFAP4 to be increased in hepatic fibrosis." (PMID 24324779, 2013). "MFAP4 is significantly upregulated in liver tissues with cirrhosis, and its expression colocalizes with α-smooth muscle actin (a myofibroblast marker) in fibrotic livers." (PMID 40492258, 2025). "To optimize stratification of patients according to MFAP4 serum level, we determined rule‐in and rule‐out cut‐offs for advanced fibrosis and cirrhosis by setting specificity (to rule‐in) or sensitivity (to rule‐out) to 90%." (PMID 32339377, 2020). "Further, human microfibril-associated protein-4 (MFAP-4) has been identified as a biomarker that can predict non-diseased liver versus cirrhosis with high diagnostic accuracy." (PMID 39189262, 2024). "We also evaluated the prognostic potential of MFAP4 among patients with ALD‐induced cirrhosis." (PMID 32339377, 2020). "As these findings potentially reflect differences in the portal pressure between the groups, we subsequently evaluated whether MFAP4 could be a prognostic marker of portal hypertension‐related hepatic decompensation in patients with cirrhosis." (PMID 32339377, 2020). "ROC curves for serum MFAP4 to diagnose advanced fibrosis and cirrhosis in all cohorts were created." (PMID 32339377, 2020). "In per‐protocol analysis, serum MFAP4 had excellent diagnostic accuracy with an AUROC of 0.88 (95% CI 0.81‐0.94) for advanced fibrosis (≥F3) and AUROC of 0.91 (95% CI 0.83‐0.98) for cirrhosis (F4) in the training cohort; similar results were seen for the validation cohort." (PMID 32339377, 2020). "Serum MFAP4 had a high NPV for advanced fibrosis and cirrhosis (91% and 97% respectively) and a moderate PPV (74% for advanced fibrosis and 58% for cirrhosis) in the training cohort." (PMID 32339377, 2020). "In the validation cohort, serum MFAP4 also had high NPV for the exclusion of advanced fibrosis (91%) and cirrhosis (93%)." (PMID 32339377, 2020). "In viral hepatitis and cirrhosis patients, transcription and protein levels experiment and histochemical analysis showed that MFAP4 levels increased significantly while progressing from non-fibrosis to severe stages." (PMID 34798886, 2021). "MFAP4 did not predict hepatic decompensation in a time‐to‐decompensation analysis in a subgroup of patients with cirrhosis." (PMID 32339377, 2020). "Finally, we demonstrated that MFAP4 was not a strong prognostic marker for hepatic decompensation in patients with early stage cirrhosis." (PMID 32339377, 2020).
breast carcinoma (8 papers, 2021 to 2025). "The association between MFAP4 and poor prognosis has been observed in a variety of cancer types, including prostate cancer, limited breast cancer, and bladder cancer." (PMID 40061958, 2025). "Also, MFAP4 has been proposed as markers of tumor progression and is linked to breast cancer, serious ovarian cancer and neuroblastoma." (PMID 36650606, 2023). "Conversely, other studies have reported significantly lower levels of MFAP4 expression in lung adenocarcinoma and breast cancer." (PMID 39822989, 2025). "Many genes such as ABCA8, MFAP4 and MAMDC2 also been potential diagnostic and prognostic biomarkers in hepatocellular carcinoma, breast cancer and ovarian cancer." (PMID 37563710, 2023).
fibrosis (6 papers, 2013 to 2025). the formation of excess fibrous connective tissue in an organ or tissue in a reparative or reactive process. "It was demonstrated that MFAP4 deficiency inhibits cardiac fibrosis and ventricular arrhythmias in mice models and therefore may act as a novel therapeutic target for the prevention of cardiac remodeling in HF." (PMID 36860278, 2023). "Compared with the BA mild fibrosis group, the median serum MFAP4 concentration in the BA severe fibrosis group was twice as high, demonstrating a statistically significant difference between the two groups (P < 0.05)." (PMID 40492258, 2025). "To corroborate our finding of the close linkage between serum MFAP4 levels and Kleiner fibrosis stage, we scored MFAP4 expression in 116 liver biopsies having varying degrees of fibrosis to validate the presence of MFAP4 in fibrotic tissue." (PMID 32339377, 2020). "It has previously been demonstrated that MFAP4 may serve as a biomarker for liver cirrhosis, where MFAP4 serum concentrations increase significantly with the progression of fibrosis development." (PMID 24349233, 2013). "Statistical analysis revealed significant differences in MFAP4 expression among CBD group, BA with mild fibrosis group, and BA with severe fibrosis group (p < 0.05)." (PMID 40492258, 2025). "MFAP4 levels were shown to differ between no to moderate fibrosis stages F0–F2 and severe stages (F3 and F4) with high statistical significance (t test on log scale, p value <2.2·10−16)." (PMID 27378383, 2016).
liver disease (6 papers, 2015 to 2024). "The increase in plasma MFAP4 level in patients with liver disease is higher than that observed in patients with heart or other diseases." (PMID 27826254, 2016). "Previous studies have found that MFAP4 may be a marker of fibrotic liver disease, active inflammation in the lungs and blood vessels, and skin disease." (PMID 39465398, 2024). "Serum microfibrillar-associated protein 4 (MFAP-4) can help distinguish patients with LC from individuals without liver disease (AUC = 0.97) using a proteomic approach." (PMID 36836704, 2023). "The physiological function of MFAP4 in liver disease is largely unknown." (PMID 26460565, 2015). "MFAP4 has not been previously assessed as a prognostic marker in liver disease." (PMID 32339377, 2020).
chronic obstructive pulmonary disease (5 papers, 2019 to 2025). A chronic and progressive lung disorder characterized by the loss of elasticity of the bronchial tree and the air sacs, destruction of the air sacs wall, thickening of the bronchial wall, and mucous accumulation in the bronchial tree. "Diseases associated with MFAP4 include Marfan syndrome, cardiovascular disorders, chronic obstructive pulmonary disease, liver fibrosis and cirrhosis, Smith-Magenis syndrome, asthma, and cancer (for review see3)." (PMID 38740766, 2024). "Microfibril-associated glycoprotein 4 (MFAP4) is a 36-kDa extracellular matrix glycoprotein with critical roles in organ fibrosis, chronic obstructive pulmonary disease, and cardiovascular disorders, including aortic aneurysms." (PMID 38740766, 2024). "Additionally, a cohort study has reported increased MFAP4 serum levels in pulmonary fibrosis caused by chronic obstructive pulmonary disease." (PMID 40243889, 2025). "Plasma MFAP4 is associated with chronic obstructive pulmonary disease (COPD) severity and may serve as a COPD biomarker." (PMID 37623890, 2023).
aortic aneurysm (4 papers, 2013 to 2024). A ruptured aneurysm located in the wall of the proximal portion of the descending aorta proceeding from the arch of the aorta. "MFAP4 has been proposed as a new candidate gene for left-sided congenital heart syndrome, and using proteome analysis, MFAP4 expression has been associated with aortic aneurysms, pulmonary hypertension and cirrhotic disease." (PMID 24349233, 2013). "One of the common manifestations of MFS is thoracic aortic aneurysm, and both MFAP4 mRNA and protein expression are upregulated in aortic aneurysm tissue from MFS patients." (PMID 35805199, 2022). "MFAP4 also mediated integrin-dependent direct monocyte recruitment important in pathological remodeling in both neointima formation and aortic aneurysms." (PMID 35805199, 2022). "Our glycoproteomics analysis revealed that MFAP4 glycosylation is enhanced in MFS patients with aortic aneurysms compared with aneurysms in patients without MFS." (PMID 31315432, 2019).